EGFL7 (EGF like domain multiple 7)
Description:
Regulates vascular tubulogenesis in vivo. Inhibits platelet-derived growth factor (PDGF)-BB-induced smooth muscle cell migration and promotes endothelial cell adhesion to the extracellular matrix and angiogenesis.
Synonyms: VE-statin; ZNEU1; NEU1
Tractability: Antibody: a drug acting on it is in phase 2 or 3 trials; UniProt places it where antibodies can reach, with high confidence; UniProt predicts a signal peptide or a membrane-spanning region; its Gene Ontology location is reachable by antibodies, with medium confidence. PROTAC: ubiquitination databases record sites on it.
Target class: Secreted protein
Gene: Protein-coding gene on chromosome 9 (136,658,284 to 136,672,679, forward strand). Ensembl gene ENSG00000172889.
Subcellular location: Secreted, extracellular space
Gene Ontology:
Molecular function: protein binding; signaling receptor binding; calcium ion binding
Biological process: negative regulation of Notch signaling pathway; positive regulation of endothelial cell proliferation; blood vessel development; vasculogenesis
Cellular component: extracellular matrix; cell surface; extracellular region
Genetic constraint (gnomAD): Loss-of-function variants: 46 observed, 32.38 expected, observed/expected ratio (o/e) 1.42, 90% interval 1.12 to 1.8. The synonymous counts are far from expectation, so gnomAD's model fits this gene poorly and the ratio says little. Missense variants: 384 observed, 339.07 expected, observed/expected ratio (o/e) 1.13, 90% interval 1.04 to 1.23. Synonymous variants: 180 observed, 138.25 expected, observed/expected ratio (o/e) 1.3, 90% interval 1.15 to 1.47.
Homologues: Orthologues: chimpanzee EGFL7 (99% identical), macaque EGFL7 (95% identical), pig EGFL7 (80% identical), mouse Egfl7 (76% identical), rat Egfl7 (75% identical), dog EGFL7 (73% identical), tropical clawed frog egfl7 (45% identical), zebrafish egfl7 (30% identical). Paralogues in human: EGFL8 (40% identical), CRIPTO (16% identical), CRIPTO3 (15% identical), CFC1 (14% identical), CFC1B (14% identical).
Diseases named in the same sentence as EGFL7 in open-access papers:
EGFL7 is named in the same sentence as 77 diseases in open-access papers, as found by Europe PMC text mining. Sharing a sentence is not in itself a finding about the gene and the disease. The quoted sentences say what the papers report.
hepatocellular carcinoma (15 papers, 2014 to 2023). A malignant tumor that arises from hepatocytes. "EGFL7 controls proliferation in melanoma, hepatocellular carcinoma, and clear cell renal cell carcinoma through one of its receptors." (PMID 33804387, 2021). "Binding of EGFL7 to EGFR enhanced cell migration of hepatocellular carcinoma cells and increased intrahepatic and pulmonary metastases in murine liver cancer models but did not alter tumor cell proliferation." (PMID 33804387, 2021). "EGFL7 is proposed to have roles in angiogenesis and the promotion of cell motility in human cancers (e.g. hepatocellular carcinoma, prostate cancer, and gastric cancer)." (PMID 32107312, 2020). "EGFL7 is one such angiogenic cytokine overexpressed in multiple malignancies such as malignant glioma, colorectal cancer, renal cell carcinoma and hepatocellular carcinoma." (PMID 29416688, 2018). "This study aims to explore the effects of microRNA-126 (miR-126) on tumor proliferation and angiogenesis of hepatocellular carcinoma (HCC) by targeting EGFL7." (PMID 27611944, 2016). "Recent studies have reported elevated expression of EGFL7 in several tumors and cancer cell lines, including kidney tumors, malignant gliomas, hepatocellular carcinomas, and colon cancers −." (PMID 24945379, 2014). "Overexpression of EGFL7 also increased tumor size in vivo, in agreement with previous studies of hepatic carcinoma." (PMID 24945379, 2014). "Subsequently, the dysregulation of EGFL7 has been found in a variety of tumors, including lung cancer, hepatocellular carcinoma, acute myeloid leukemia and malignant pleural mesothelioma, suggesting that EGFL7 participates in tumorigenesis through a wide range of effects." (PMID 35494025, 2022). "Moreover, it has been reported that EGFL7 directly increases tumor cell migration in hepatocellular carcinoma and acute myeloid leukemia." (PMID 32117731, 2020). "Recent studies showed that EGFL7 is involved in the pathology of certain solid tumors, including breast cancer, epithelial ovarian cancer, hepatocellular carcinoma, colorectal cancer, acute myeloid leukemia, and malignant glioma, However, evidence regarding the role of EGFL7 in OS is still sparse." (PMID 32117731, 2020). "This study intends to explore the effects of microRNA-126 (miR-126) on cell proliferation, apoptosis, and tumor angiogenesis in hepatocellular carcinoma (HCC) by regulating epidermal growth factor-like domain 7 (EGFL7) through extracellular signal-regulated kinase (ERK) signaling." (PMID 28881749, 2017). "However, deficiency of Arid1a in mouse HCC (hepatocellular carcinoma) cells did not alter several of the angiogenesis-related genes, including Vegfa, Fgf2, Egfl7, Sdf1, Hif1a, Hif2a and Ang1." (PMID 38017409, 2023). "Interestingly, EGFL7 can also bind to the EGFR at cell membrane and this interaction enhances cell migration of hepatocellular carcinoma cells through FAK phosphorylation." (PMID 37853459, 2023).
glioma (12 papers, 2011 to 2023). A benign or malignant brain and spinal cord tumor that arises from glial cells (astrocytes, oligodendrocytes, ependymal cells). "Quantitative proteomics was adopted to characterize 200 paired EGFR-positive and EGFR-negative glioma tissues of all pathological types, and EGF-like domain multiple 7 (EGFL7) was identified as a potential diagnostic biomarker and therapeutic target." (PMID 34095463, 2021). "High expression levels of EGFL7 transcripts were associated with higher tumor grades in colon carcinoma and glioma, but the EGFL7 protein was mainly secreted by endothelial cells." (PMID 32117731, 2020). "Reduced survival caused by the ectopic expression of EGFL7 in experimental gliomas was blocked by the specific inhibition of integrin α5β1." (PMID 30065025, 2018). "In glioma, a continuous Egfl7 autocrine flow line was the cause of oncogenic activation of EGFR." (PMID 37480091, 2023). "Tumor EC-derived EGFL7 promotes glioma growth in experimental glioma models and stimulates tumor vascularization with the generation of mature vessels covered with pericytes and smooth muscle cells." (PMID 33804387, 2021). "EGFL7 is secreted by glioma blood vessels and increases angiogenesis in GB, suggesting inhibition of EGFL7 as a possible treatment strategy." (PMID 30934929, 2019). "Contrary to EGFL7, low expression levels of miR‐126 have been described to correlate with increased migration of glioma cells and worse clinical outcome." (PMID 30065025, 2018). "The specificity of the anti‐human EGFL7 antibody applied was confirmed by costaining of glioma specimens with alternative anti‐EGFL7 antibodies from different sources which yielded 100% overlap." (PMID 30065025, 2018). "T2‐weighted MRI confirmed that all animals developed tumors, and the analysis of T1‐weighted images illustrated that in EGFL7‐expressing tumors less Gadovist leaked into the glioma mass." (PMID 30065025, 2018). "The syngeneic GL261 as well as the U87 xenograft model have been selected due to their dependency on blood vessel growth, which makes them excellent tools to study the impact of EGFL7 on angiogenesis in a glioma‐like environment." (PMID 30065025, 2018). "In conclusion, EGFL7 expression in glioma specimens was characteristic of blood vessels and occurred independently of miR‐126/126*." (PMID 30065025, 2018). "Although the conclusion of this last study showing that low EGFL7 levels improve survival of mice in an experimental glioma model is in agreement with our findings, it was compiled by EGFL7 knockdown in U87 cells." (PMID 30065025, 2018). "In order to test this, EGFL7, stroma and glioma marker expression was analyzed by qRT–PCR in patient‐derived biopsies and the derived spheroid‐based xenografts." (PMID 30065025, 2018). "EGFL7‐inhibition using a specific blocking antibody reduced the vascularization of experimental gliomas and increased the life span of treated animals, in particular in combination with anti‐VEGF and the chemotherapeutic agent temozolomide." (PMID 30065025, 2018). "Quantification of EGFL7 staining in glioma specimens yielded 25–40% positive intratumoral blood vessels in each specimen." (PMID 30065025, 2018). "Subsequently, human EGFL7 mRNA levels in glioma specimens, human stemlike brain tumor‐propagating cells (BTPCs) or glioma cells (GCs) were quantified by quantitative reverse transcriptase–polymerase chain reaction (qRT–PCR)." (PMID 30065025, 2018). "Further, blocking EGFL7 with a specific antibody in experimental glioma models yielded a significant increase in median survival time." (PMID 30065025, 2018). "While CpG island 1 within the EGFL7 promoter was found unmethylated in almost all glioma samples, CpG island 2 responsible for miR‐126/126* expression was mostly methylated with the exception of the histone H3 G34‐mutant GBM subgroup (G34R)." (PMID 30065025, 2018). "EGFL7 expression promoted glioma growth in experimental glioma models in vivo and stimulated tumor vascularization." (PMID 30065025, 2018).
glioma (continued). "In conclusion, EGFL7 expression enhanced experimental glioma growth and decreased the life span of EGFL7‐positive tumor‐bearing mice." (PMID 30065025, 2018). "In order to assess the role of endogenous EGFL7 for glioma formation, BTPC11 cells underwent shRNA‐based knockdown studies to avoid affecting miR‐126 expression." (PMID 30065025, 2018). "Expression analysis revealed that EGFL7 was present in malignant glioma of various types but was lost in cultured glioma cells." (PMID 30065025, 2018). "Subsequent immunohistochemical analysis (IHC) of healthy brain and glioma specimens revealed that blood vessels (and neurons in the healthy brain) stained strongly positive for EGFL7." (PMID 30065025, 2018). "Data show that the presence of EGFL7 increased both the amount and maturation state of intratumoral glioma vessels." (PMID 30065025, 2018). "We can conclude that at least in miR-126, a co-regulated expression with EGFL7 appears to be disrupted in gliomas." (PMID 21655185, 2011). "However, the anti‐EGFL7 antibody applied in this study had been optimized using U251 glioma cells as a positive control, a cell line that turned out to be negative for EGFL7 expression in our analyses." (PMID 30065025, 2018). "However, a comprehensive functional study on the role of EGFL7 and miR‐126/126* in glioma has been missing so far." (PMID 30065025, 2018). "In order to assess the methylation status of the EGFL7 promoter in glioma cells, several BTPCs as well as LN229 cells were treated with a combination of DNA methyltransferase inhibitor 5‐Aza‐dC (Aza) and histone deacetylase inhibitor 4‐phenylbutyric acid (PBA)." (PMID 30065025, 2018). "Upon glioma implantation, these mice were treated twice a week by intraperitoneal injection of an α5β1‐inhibiting antibody or isotype control, which increased the survival of animals for about 4.5 days, verifying that EGFL7 affected glioma growth dependent on integrin α5β1." (PMID 30065025, 2018). "Increased expression of EGFL7 has been described for tumors of various origins; therefore, we wondered about the influence of high EGFL7 levels on experimental glioma growth." (PMID 30065025, 2018). "Data above offered the possibility that anti‐EGFL7 treatment may affect the tumor vasculature of experimental glioma." (PMID 30065025, 2018). "Experimental glioma models were engaged to understand whether the influence of EGFL7 on EC was relevant for the vascularization of malignant brain tumors." (PMID 30065025, 2018). "Moreover, GL261 glioma cells ectopically expressing mouse EGFL7 were intracranially implanted into the striatum of WT mice." (PMID 30065025, 2018). "NFAT5/SBF2-AS1/miR-338-3p/EGFL7 pathway may provide novel targets for glioma anti-angiogenic treatment." (PMID 28983240, 2017). "Interestingly, it has been demonstrated that EGFL7 could activate both AKT pathways in glioma and gastric cancer." (PMID 31245291, 2019). "Furthermore, a recent study claims an EGFR‐dependent effect of EGFL7 on glioma growth." (PMID 30065025, 2018). "Increased EGFL7 levels promote glioma angiogenesis and may predict poor prognosis of GBM patients." (PMID 28983240, 2017). "It is reported that SBF2-AS1 is more highly expressed in IDH-wildtype than in IDH-mutant glioma and its knockdown in glioblastoma upregulates miR-338-3p, but downregulates EGF-like domain multiple 7 (EGFL7), thereby inhibiting angiogenesis." (PMID 36819921, 2023). "In sum, inhibition of EGFL7 or VEGF alone or in combination resulted in fewer and less mature blood vessels in experimental gliomas as well as an increase in animal survival time, in particular in combination with TMD." (PMID 30065025, 2018). "In order to evaluate the oncogenic potential of endogenous EGFL7 in vivo, GL261 glioma cells were intracranially implanted into the striatum of EGFL7‐knockout (KO) mice and respective wild‐type (WT) litters." (PMID 30065025, 2018).
glioma (continued). "At this stage, it can be concluded that a combinatorial regimen of anti‐EGFL7 and anti‐VEGF antibodies increased the median survival in angiogenesis‐dependent syngeneic and xenograft glioma models." (PMID 30065025, 2018). "EGFL7-expression levels were found to correlate with a higher tumor grade in gliomas and colon cancer, not influencing the prognosis." (PMID 35630004, 2022). "Primary glioma specimens displayed significant levels of EGFL7, while BTPCs and GCs expressed little to no EGFL7." (PMID 30065025, 2018). "Subsequent analyses revealed that EGFL7 secretion was indeed a feature of glioma blood vessels but not the tumor cells themselves." (PMID 30065025, 2018). "Findings suggest that EGFL7 was indeed expressed in glioma specimens, while miR‐126/126* were not, but expression was absent in glioma cells." (PMID 30065025, 2018). "Furthermore, expression, promoter, and biological analyses allow for the conclusion that the expression of EGFL7 and miR‐126 were not directly coupled in glioma specimens." (PMID 30065025, 2018). "This suggests that brain parenchymal or stromal but not glioma cells produced EGFL7." (PMID 30065025, 2018). "We found that the encoded extracellular matrix protein epidermal growth factor‐like protein 7 (EGFL7) was secreted by glioma blood vessels but not glioma cells themselves, while no major role could be assigned to the parasitic miRNAs miR‐126/126*." (PMID 30065025, 2018). "MRI analysis of the experimental brain tumors demonstrated an increased amount of Gadovist in the glioma mass and brain parenchyma subsequent to anti‐EGFL7, anti‐VEGF, or combinational treatment, indicating increased blood vessel leakage upon inhibition of EGFL7 and VEGF." (PMID 30065025, 2018). "Therefore, it was tested whether or not expression of EGFL7 and miR‐126/126* occurred in glioma specimens." (PMID 30065025, 2018). "In order to assess whether or not anti‐EGFL7 treatment offers a benefit for glioma treatment in a clinical setting, the influence of a chemotherapy regimen on anti‐VEGF and anti‐EGFL7 treatment was studied subsequent to intrastriatal implantation of U87 in NOD SCID mice." (PMID 30065025, 2018).
lung carcinoma (9 papers, 2015 to 2023). "We showed that the expression of miR-126 and EGFL7 is concomitantly downregulated in NSCLC through methylation and that the eQTL-missense polymorphism of EGFL7 is associated with lung cancer risk in a Han Chinese population." (PMID 35494025, 2022). "In the current study, we firstly found that rs2297538 was associated with the expression of miR-126 and EGFL7 mRNA in lung cancer tissues." (PMID 35494025, 2022). "Upregulation of EGFL7 activates NOTCH signaling in lung cancer cells, which slows down the decrease of c-Myc caused by EGFR inhibition, thereby helping the survival of cancer cells." (PMID 36309484, 2022). "Based on these evidences, altered expression of EGFL7 in endothelial cells and alveolar type 2 cells could be associated with the lung cancer susceptibility." (PMID 35494025, 2022). "Furthermore, pre-clinical studies have demonstrated a relationship between high EGFL7 expression and increased risk of metastatic spread in hepatocellular, breast, and lung cancer." (PMID 25592646, 2015). "Moreover, the risk rs2297538 G allele might be correlated with lower expression of miR-126 and EGFL7 mRNA in lung cancer tissues, which indicated that reduced expression of miR-126 and EGFL7 might be risk factors for NSCLC." (PMID 35494025, 2022). "The activation of EGF like domain multiple 7 (EGFL7)/Notch signalling in lung cancer cells, triggers resistance to EGFR inhibitors." (PMID 37569598, 2023). "To validate these results, we tested miR-126 and EGFL7 mRNA expression in lung cancer tissue along with matched adjacent normal tissue from 46 NSCLC patients using qRT–PCR." (PMID 35494025, 2022). "EGFL7 is expressed in a variety of tumors, including liver cancer, malignant glioma, breast cancer, lung cancer, and pancreatic cancer." (PMID 36072982, 2022). "Differential methylation analysis indicated that methylation levels of multiple CG loci in EGFL7 were significantly higher in the lung cancer samples than in the normal samples (P < 0.01)." (PMID 35494025, 2022). "We found that EGFL7 and miR-126 expression decreased significantly in lung cancer tissue compared with adjacent normal tissue (P = 3x10-4 and P < 1x10-4, respectively), which was consistent with in silico analysis and previous results." (PMID 35494025, 2022). "In silico analysis of EGFL7 mRNA expression indicated that the expression of EGFL7 in lung cancer tissue was lower than that in normal lung tissue (P < 0.01)." (PMID 35494025, 2022). "Moreover, EGFL7 mRNA and miR-126 were significantly upregulated after treatment with the DNA demethylating agent 5-aza-2′-deoxycytidine (5-Aza-CdR) in lung cancer cell lines." (PMID 35494025, 2022). "To determine whether rs2297538 was related to the expression of nearby genes, we conducted eQTL analysis between this SNP and miR-126 and EGFL7 mRNA expression using qRT–PCR in 46 lung cancer tissues." (PMID 35494025, 2022). "Previous investigations have reported that microRNA-126 (miR-126) and its host gene, epidermal growth factor-like domain-containing protein 7 (EGFL7) are involved in lung cancer progression, suggesting EGFL7 and miR-126 play a joint role in lung cancer development." (PMID 35494025, 2022). "Accordingly, increased tumorigenicity of EGFL7 was observed in models of breast and lung cancer." (PMID 30065025, 2018). "In addition, decreased expression of EGFL7 may confer a risk of NSCLC via other biological mechanisms, such as altering the mitochondrial function of lung cancer cells." (PMID 35494025, 2022). "MiR-126 has been widely reported as a tumour suppressor in lung cancer due to targeting IRS1, EGFL7, Crk, and SLC7A51318, or by means of inhibiting angiogenesis and lung metastasis during lung cancer." (PMID 29127370, 2017).
lung carcinoma (continued). "Our data indicated that methylation levels of several CG loci in EGFL7 were significantly higher in the lung cancer samples than in the normal samples and 5-Aza-CdR treatment of NSCLC cell lines could result in up-regulation of EGFL7 mRNA expression." (PMID 35494025, 2022). "In addition, miR-126 inhibits cell migration and invasion in lung cancer by targeting VEGFA and EGFL-7." (PMID 26274316, 2015).